CSAD (cysteine sulfinic acid decarboxylase)
Description:
Catalyzes the decarboxylation of L-aspartate, 3-sulfino-L-alanine (cysteine sulfinic acid), and L-cysteate to beta-alanine, hypotaurine and taurine, respectively. The preferred substrate is 3-sulfino-L-alanine. Does not exhibit any decarboxylation activity toward glutamate.
Synonyms: CSD; CSADC; PCAP
Tractability: Small molecule: it has a high-quality binding pocket. Antibody: the Human Protein Atlas places it where antibodies can reach. PROTAC: ubiquitination databases record sites on it.
Gene: Protein-coding gene on chromosome 12 (53,157,663 to 53,180,933, reverse strand). Ensembl gene ENSG00000139631.
Subcellular location (Human Protein Atlas): Endoplasmic reticulum; Plasma membrane; Vesicles
Pathways (Reactome):
Metabolism: Degradation of cysteine and homocysteine
Gene Ontology:
Molecular function: aspartate 1-decarboxylase activity; sulfinoalanine decarboxylase activity; carbon-carbon lyase activity; pyridoxal phosphate binding
Biological process: L-cysteine catabolic process; taurine biosynthetic process
Cellular component: cytoplasm
Genetic constraint (gnomAD): Loss-of-function variants: 48 observed, 62.82 expected, observed/expected ratio (o/e) 0.76, 90% interval 0.61 to 0.97. The upper end of that interval is the gene's LOEUF score, 0.97, which puts it in group 4 of 6, group 1 being the genes least tolerant of losing a copy. Missense variants: 610 observed, 665.14 expected, observed/expected ratio (o/e) 0.92, 90% interval 0.86 to 0.98. Synonymous variants: 245 observed, 262.54 expected, observed/expected ratio (o/e) 0.93, 90% interval 0.84 to 1.04.
Homologues: Orthologues: chimpanzee CSAD (99% identical), macaque CSAD (98% identical), dog CSAD (90% identical), pig CSAD (90% identical), mouse Csad (90% identical), rat Csad (90% identical), guinea pig CSAD (87% identical), rabbit CSAD (87% identical), tropical clawed frog csad (66% identical), zebrafish csad (63% identical), Drosophila melanogaster b (52% identical). Paralogues in human: GADL1 (60% identical), GAD1 (52% identical), GAD2 (51% identical), DDC (21% identical), HDC (21% identical), PDXDC1 (19% identical), SGPL1 (19% identical).
Diseases named in the same sentence as CSAD in open-access papers:
CSAD is named in the same sentence as 28 diseases in open-access papers, as found by Europe PMC text mining. Sharing a sentence is not in itself a finding about the gene and the disease. The quoted sentences say what the papers report.
prostate carcinoma (5 papers, 2004 to 2023). A carcinoma that arises from epithelial cells of the prostate gland. "For the genes that we show are involved in prostate cancer prognosis (see further section), CSAD had increased expression in prostate cancer (fold-change = 1.61, FDR < 0.001), while the expression of SERINC3 did not change according to the criteria used." (PMID 36831650, 2023). "By using a machine learning approach, we found that the expression of the genes CSAD and SERINC3 discriminates between better and worse prognosis (low and high risk) for progression-free survival (PFS) of prostate cancer patients when they are stratified according to the Gleason score." (PMID 36831650, 2023). "Functional studies on CSAD and SERINC3 genes and their regulators are needed to further delineate their roles in prostate cancer, which would reveal their potential for further interventions." (PMID 36831650, 2023).
Hepatic steatosis (3 papers, 2022 to 2025). Steatosis is a term used to denote lipid accumulation within hepatocytes. "Hepatic NMNAT1 null mice exacerbated alcohol-induced hepatic steatosis and liver injury by inhibiting the cysteine sulfinic acid decarboxylase (CSAD)–regulated taurine pathway in a NAD+-dependent manner." (PMID 40577472, 2025). "Some studies have reported that overexpression of CSAD improves fatty liver, but it is less commonly reported in disease progression to e.g., NASH and HCC." (PMID 38515461, 2024).
glioblastoma (2 papers, 2021 to 2022). The most malignant astrocytic tumor (WHO grade IV). "Additionally, homocysteic acid (an inhibitor of cysteine sulfinic acid decarboxylase — hypotaurine production) can inhibit the proliferation of glioblastoma cell lines, and some in vivo studies have confirmed that hypotaurine could be a targetable oncometabolite in glioblastomas." (PMID 35029792, 2021). "Two further enzymes that could be connected to changing hypotaurine levels were either not part of our RNA data set (glutamate decarboxylase like 1 [GADL1]) or only slightly increased in the IDH1-mut but not in IDH1-WT glioblastoma group (cysteine sulfinic acid decarboxylase [CSAD])." (PMID 34941573, 2022).
hepatocellular carcinoma (2 papers, 2020 to 2023). A malignant tumor that arises from hepatocytes. "In this study, we found that METTL14 may inhibit the progression of hepatocellular carcinoma (HCC) by up‐regulating the expression levels of cysteine sulfinic acid decarboxylase, glutamic‐oxaloacetic transaminase 2, and suppressor of cytokine signaling." (PMID 31943856, 2020). "In hepatocellular carcinoma (HCC), METTL14 was identified to be involved in the malignant progression of HCC by regulating m6A downstream targets, including cysteine sulfinic acid decarboxylase (CSAD), glutamic- oxaloacetic transaminase 2 (GOT2), and suppressor of cytokine signaling 2 (SOCS2)." (PMID 35731272, 2023).
liver cancer (2 papers, 2024 to 2025). An epithelial or non-epithelial malignant neoplasm that arises from the liver. "Among these, six genes were significantly differentially expressed between liver cancer tissue and adjacent normal tissue (CSAD, SLC16A11, LILRA2, IMMP2L, GLP2R, and DHDH)." (PMID 38927691, 2024). "In liver cancer, multiple different groups’ investigations showed that METTL14 inhibits EMT, invasion and metastasis of liver cancer cells by regulating m6A-modified target mRNAs such as EGFR/PI3K/AKT, DGCR8/primiR-126, USP48/SIRT6/glycolysis, CSAD, GOT2 and SOCS2." (PMID 40734692, 2025).
steatosis (2 papers, 2022 to 2024). Increased lipid within the cytoplasm of cells. "However, among the limited number of genes showing both gene expression and methylation variation, Cysteine Sulfinic Acid Decarboxylase CSAD and FGF21 were previously noted in two independent studies to be able to mitigate lipid accumulation and steatosis in HFD-treated mice." (PMID 39770043, 2024).
Stroke (2 papers, 2022). Sudden impairment of blood flow to a part of the brain due to occlusion or rupture of an artery to the brain. "Therefore, CSAD is a potential target of EDA therapy for stroke." (PMID 35237165, 2022). "In summary, taurine and CSAD have a critical role in inhibiting ECs apoptosis, which might be an important metabolism mechanism of EDA treatment stroke." (PMID 35237165, 2022).
colitis (1 paper, 2023). Inflammation of the colon. "We observed several upregulated genes associated with colitis and IBD development, including ABCA2, Acss1, Araf, CSAD, Ilf3, and TRAFD1, showing similar fold change patterns across treatment groups." (PMID 37909786, 2023).
Hepatic fibrosis (1 paper, 2025). The presence of excessive fibrous connective tissue in the liver. "Therefore, we reveal that FAN can inhibit hepatic fibrosis by increasing taurine content by raising the protein levels of CSAD, a key enzyme of taurine synthesis." (PMID 40910002, 2025).
kidney tumors (1 paper, 2015). "In fact, we found that taurine and sorbitol synthesis genes, CSAD and AKR1B1 respectively, are upregulated in many kidney tumors." (PMID 26439621, 2015).
viral infection (1 paper, 2025). "CSAD KO mice in B6 background initiate stronger inflammatory responses and are more vulnerable to viral infections, exhibiting a phenotype resembling 129 mice." (PMID 40952115, 2025). "CSAD, an enzyme in the taurine synthesis pathway, inhibits excessive inflammatory responses after viral infection or stimulation by interacting with IKKα of the NF-κB signaling pathway, thus limiting the downstream activation of signaling and reducing the cytokine and chemokine gene expression." (PMID 40952115, 2025). "CSAD inhibits the NF-κB signaling pathway during various virus infections and stimulations." (PMID 40952115, 2025). "In this study, we found that cysteine sulfinic acid decarboxylase (CSAD), an essential enzyme in the taurine synthesis pathway, inhibits excessive inflammation after viral infection." (PMID 40952115, 2025).
cancer (4 papers, 2017 to 2025). A tumor composed of atypical neoplastic, often pleomorphic cells that invade other tissues. "In summary, these findings indicate that CSAD is highly expressed in ccRCC and plays a critical role in promoting cancer cell proliferation and migration in vitro." (PMID 41584585, 2025). "Interestingly, we find that CSA is differentially metabolized in cancer cells and mouse embryonic fibroblasts, which correlates with differential expression of CSAD and GOT1." (PMID 31107239, 2019).
tumor (2 papers, 2017 to 2025). "qPCR analysis revealed upregulated CSAD expression in all four tumor cell lines, with the highest level observed in 769-P cells and the lowest in OSRC2 cells." (PMID 41584585, 2025). "qPCR analysis revealed that CSAD, IL4I1, and P4HA3 were significantly upregulated in tumor specimens, whereas PSAT1 expression was notably reduced in ccRCC tissues (p<0.05)." (PMID 41584585, 2025).
immune system diseases (1 paper, 2023). "On the other hand, the genes ITGB7, CSAD, and TRPM2 are associated with immune system diseases that accompany skin deficiencies." (PMID 37990155, 2023).
infection (1 paper, 2023). The state of being infected such as from the introduction of a foreign agent such as serum, vaccine, antigenic substance or organism. "Specifically, out of three enzymes involved in taurine synthesis, namely GAD, CSAD and FMO1, only FMO1 was found to have a substantial impact over CHIKV infection and oxidative stress during the infection." (PMID 37130109, 2023).
inflammation (1 paper, 2023). Aberrant reaction of the microcirculation characterized by movement of fluid and leukocytes from the blood into extravascular tissues. "The gene CSAD catalyzes the decarboxylation of cysteine sulfinate to hypotaurine, eventually to taurine, with cysteine shown to be essential in the recovery of the host from chronic colon inflammation and reduced IBD symptoms." (PMID 37909786, 2023).
metabolism disorders (1 paper, 2022). "Further experimental results showed that CSAD was downregulated in HFD-fed mice, even for 6 weeks, the earliest time for high-fat-induced metabolism disorders." (PMID 36555571, 2022).
CSAD also shares sentences with these, for which no sentence is quoted: Obesity (2 papers); autoimmune disease (1); breast carcinoma (1); cardiomyopathy (1); colorectal cancer (1); Hypotrichosis 13 (1); pheochromocytoma (1); retinal degeneration (1); Sepsis (1); stiff-person syndrome (1); type 1 diabetes (1).